MTOR (mechanistic target of rapamycin kinase)
Diseases named in the same sentence as MTOR in open-access papers (continued):
Sharing a sentence is not in itself a finding about the gene and the disease.
cancer (continued). "In addition, pitavastatin suppressed Ras/Raf/MEK/ERK and PI3K/Akt/mTOR signaling and associated protein prenylation, both of which have been implicated in promoting cancer progression." (PMID 35884561, 2022). "The mTOR signaling pathway senses and integrates a variety of environmental cues to regulate cellular homeostasis through mechanisms which include autophagy, and it is implicated in several pathologies including cancer." (PMID 35456001, 2022). "This is partly due to the incomplete understanding of the mechanisms underlying mTOR activation and mTORC1 addiction in cancer cells, which compromises the identification of effective biomarkers for predicting potentially responsive patients and guiding clinical implications." (PMID 36438486, 2022). "p-mTOR-Ser2448 was previously associated with mTORC1 activation in cancer cell lines." (PMID 34855620, 2022). "The activation of mTOR is associated with poor prognosis in cancer patients." (PMID 35408483, 2022). "In addition to cancer cells, mTOR activation is essential for various types of cells, and an irregular activation of mTOR was found to be closely related to diseases caused by excessive cell growth and proliferation." (PMID 34431239, 2022). "Notably, this class of compounds show preclinical efficacy even on cancer cells bearing constitutively active mTOR mutations that cause resistance to mTOR kinase inhibitors." (PMID 36077374, 2022). "The mammalian target of rapamycin (mTOR) regulates a number of cellular processes, including cell survival, proliferation, and metabolism, and activation of mTOR signaling pathways is associated with human cancer." (PMID 35216362, 2022). "Whether mTOR pathway mutations affect the antioxidant therapy in cancers is to be answered in future investigations." (PMID 35642038, 2022). "We checked whether the different responses to OXPHOS inhibition are associated with different mTOR activities between cancer cells sensitive or resistant to OXPHOS inhibition." (PMID 36382559, 2022). "which again implicated the PI3K/Akt/mTOR pathway as key player in cancer radioresistance." (PMID 36233505, 2022). "AKT/PI3K/mTOR pathway activation causes cancer development and resistance to anticancer treatments." (PMID 36144625, 2022). "Low extracellular pH is associated with positively charged amino acids and a known hallmark of cancer arising from enhanced glycolysis, production and altered lactate metabolism, resulting in altered mTOR pathway activation, ultimately regulating cancer cell metabolism." (PMID 35954325, 2022). "Although mutation of mTOR is rarely reported in cancer, it is a converging point from many oncogenic nodes, such as mutations leading to the activation of the phosphatidyliositoal-3 kinase (PI3K)-Akt pathway and the rat sarcoma (Ras)-driven mitogen-activated protein kinase (MAPK) pathway." (PMID 35955931, 2022). "Many mutations in the mTOR pathway leading to its hyperactivity have been identified in cancer." (PMID 35740927, 2022). "To test this hypothesis, we performed a two-stage survival association study and identified an 8-gene signature in mTOR pathway whose mutation was associated with better survival in cancer patients received ICI treatment." (PMID 35642038, 2022). "The genetic data suggest that resistance to ibrutinib in FL may be related to epigenetic modification and telomere maintenance, in addition to cancer‐associated signaling pathways (mTOR, JAK/STAT, NF‐κB)." (PMID 34791836, 2022). "This review summarized oncogenic PI3K/Akt/mTOR pathway alterations in cancer and various cancer hallmarks associated with the PI3K/AKT/mTOR pathway, such as cell proliferation, autophagy, apoptosis, angiogenesis, epithelial-to-mesenchymal transition (EMT), and chemoresistance." (PMID 35402264, 2022).
cancer (continued). "The mTOR pathway, as the nutrient sensor for the cell, regulates various aspects of metabolism, and it has recently been implicated in metabolic reprogramming of model cancer cells that were subjected to a glycolytic block with 2-deoxyglucose (2DG)." (PMID 35681744, 2022). "The degree of dependence on mTOR activation varies, and even among patients with similar mutation profiles, the outcomes associated with mTOR inhibitor therapy have been reported to vary across different cancer types." (PMID 35883111, 2022). "Cancer-associated dysregulation of cell proliferation is known to be related to mTOR signaling." (PMID 36012443, 2022). "SETD2, BAP1, and MTOR possessed higher mutation frequencies in the high-risk group than in the low-risk group implying that these three cancer-driven mutations may promote the progression of KIRC." (PMID 37342680, 2022). "Thus, SENP1 overexpression caused mTOR pathway activation, increased cancer stemness, and resistance to the mTOR inhibitor." (PMID 36284084, 2022). "Together, mTOR expression has been associated with poor prognosis in some types of cancer, so mTOR inhibitors could represent a therapeutic alternative in order to improve the effectiveness of current treatments." (PMID 35745875, 2022). "Arginine directly activates mTOR, a nutrient signaling kinase implicated in cancer." (PMID 35626143, 2022). "Our data uncovered the mechanism underlying mTOR overactivation in cancers and suggested that targeting mTOR/ULK1/autophagy could be an effective strategy for METTL1 overactive ESCC treatment." (PMID 35304469, 2022). "Thus, mTOR signaling pathway represents a potential therapeutic target for preventing HPV-associated cancers." (PMID 35938153, 2022). "PI3K/AKT/mTOR pathway is well-known as a crucial intracellular signaling pathway in tumorigenesis, and its activation is closely associated with the malignant hallmarks of cancer cells." (PMID 36349192, 2022). "iv.Any clinically relevant mTOR mutations that increase mTOR's catalytic activity could drastically diminish the efficiency of such inhibitors in cancer cells." (PMID 36109789, 2022). "Moreover, we provide a comprehensive update on the mechanisms underlying the effects of combining mTOR inhibitors with synthetic and natural compounds as cancer preventive and therapeutic agents." (PMID 36428613, 2022). "Considering that rpS6 is a downstream effector of both the ERK and the mTOR pathways linked to cancer development and metastasis, the mTOR-selective inhibitor rapamycin was used to investigate the involvement of the mTOR pathway in the EGF-mediated signalling transduction." (PMID 35884900, 2022). "Additionally, mTOR signalling was also associated with cancer, by way of increased pathway activity characteristic for malignant tumours." (PMID 35205287, 2022). "Of interest, the mTOR signaling pathway is associated with numerous immunosuppressive cells that contribute substantially to the development of a suitable tumor microenvironment for cancer progression and drug resistance." (PMID 35327484, 2022). "An examination of HCMV-associated alterations to PI3K/Akt/mTOR signaling following infection could yield intriguing insights in relation to cancer." (PMID 35062307, 2022). "Note that mTOR has recently been implicated in regulating GLUT1 in cancer cells and has been considered a potential therapeutic target, although the association between mTOR and glucose transporters in the PT remains unclear." (PMID 36299884, 2022). "Promoters of cellular growth, such as Fibroblast activation protein (FAP), cancer-associated fibroblasts (CAFs), and fibronectin, induce the activation of the mechanistic target of rapamycin (mTOR) and the secretion of cytokines, such as IL6 and CXCL12, which recruit T-cells CD4+." (PMID 35743107, 2022).
cancer (continued). "It is interesting to speculate this may be in part due to the alteration of over-activity in the Ras/BRAF/MEK/ERK and PI3KCA/AKT/mTOR pathways, which are commonly affected by gain-of-function mutations in various types of cancer and VAs." (PMID 35574555, 2022). "Importantly, the underlying molecular mechanism of ITZ’s anti-cancer effect has been reported via inhibiting hedgehog signaling, Wnt pathway and/or reducing mTOR expression, recognized as an mTOR inhibitor." (PMID 35517785, 2022). "In addition, we suggest pathomorphological and analytical studies relating to metabolic alterations, mTOR activity, and their associations which are necessary to improve understanding of tumor heterogeneity and expand the therapeutic management of cancer." (PMID 35029792, 2021). "Proteins in the mTOR pathway are among the most frequently mutated genes in cancers." (PMID 33668092, 2021). "In cancer cells miR-126-5p inhibited PTEN expression causing PI3K/Akt/mTOR pathway activation." (PMID 33814008, 2021). "Interestingly, 3 out of 5 tumor samples with dA-AL-I detected in paired normal tissues harbored mutations in mTOR, which serves as a cancer driver gene, at a higher frequency." (PMID 35071023, 2021). "For example, genes assigned to ubiquitous peaks were responsible for the canonical role of SREBF1 in lipid metabolism, whereas transcripts assigned to ESCC-specific peaks were enriched in many cancer-associated signaling pathways, including ErbB and mTOR pathways." (PMID 34272396, 2021). "Since the PI3K/AKT/mTOR axis is the fundamental for the regulation of cell proliferation and linked to multidrug resistance in cancer 33,34, we next investigated whether loss-of-USP32 can modulate this pathway." (PMID 34815782, 2021). "Valine, as well as other branched chain amino acids (BCAAs), also plays an important role in activating the mechanistic/mammalian target of rapamycin (mTOR) axis, a signalling pathway associated with cell growth, proliferation, and survival, important features of cancer development." (PMID 33926456, 2021). "The AKT/mTOR signaling pathway is associated with functioning of the cancer stemness features." (PMID 34681918, 2021). "In addition to regulating mTOR and iNOS pathways, sestrin 2 has been shown to promote cancer cell apoptosis by targeting X-linked inhibitor of apoptosis protein (XIAP) and suppress cell migration and invasion by targeting hypoxia inducible factor-1α (HIF-1α)." (PMID 34784907, 2021). "Members of the PI3K/Akt/mTOR pathway are often mutated and activated in cancer." (PMID 34916492, 2021). "Since overexpression or amplification of MYC/MYCN and activation of mTOR signaling are often associated with chemoresistance in many cancers including NB, we also wanted to see whether inhibition of these signaling pathways helps to chemosensitize NB cells." (PMID 34565342, 2021). "PI3K/Akt/mTOR signaling pathway mutation is common in various cancer types." (PMID 34356634, 2021). "Furthermore, molecular changes in PI3K/AKT/mTOR pathway, containing mutations, copy number, protein, or RNA, have been detected in 11,219 human cancers (32 major cancer types included)." (PMID 34568005, 2021). "The IC50 of this DEPTOR mutant was comparable to the wild-type DEPTOR for both the wild-type mTORC1 and mTORC1 with an activating cancer-associated mTOR mutation (A1459P), so interaction between these S/T residues and mTORC1 is not important for inhibition by DEPTOR." (PMID 34519269, 2021). "Several studies reported that cancer risk and progression is associated with mTOR activation." (PMID 35008275, 2021). "Additionally, protein kinase B (AKT) activity and virus-induced activation of the pathway regulated by the mammalian target of rapamycin (AKT/mTOR axis) is linked to resistance in various cancers." (PMID 34696274, 2021).
cancer (continued). "The PI3K/Akt/mTOR pathway is positively associated with cell proliferation and survival, and any dysregulation of this signaling pathway significantly mediated the progression of various cancers, including TNBC." (PMID 33916931, 2021). "Additionally, data has shown that irregularity in the phosphatidylinositol 3-kinase (PI3K)/Akt/mTOR-signaling pathway has been implicated in various human cancer types including PC." (PMID 34452154, 2021). "mTOR signaling deregulation is also implicated in cancer progression." (PMID 34885006, 2021). "In addition, PI3K signaling is associated with the regulation of several metabolic effects through its activity on Akt and mTOR, as supported by a shift towards a highly glycolytic phenotype observed in cancer cells by PIK3CA mutations." (PMID 34208576, 2021). "In fact, CMap analysis identified PI3K/Akt/mTOR inhibitors as potentially suitable candidate compounds for NB treatment, because they were able to revert the expression of genes in different cancer cell lines that we previously found to be associated with hypoxia in NB patients." (PMID 34199959, 2021). "Moreover, mTOR/p-mTOR expression was also significantly associated with worse overall survival, disease-free survival, and cancer-specific survival of patients with ESCC." (PMID 33572326, 2021). "Misregulation of mTOR signaling has been previously implicated in various forms of cancer." (PMID 33541283, 2021). "Fisetin causes death of cancer cells, which is associated with mTOR inhibition." (PMID 34504654, 2021). "ENO1 is a glycolysis-associated enzyme that participates in various cancers; therefore, we focused on glycolysis-associated pathways; the mTOR/HIF1α pathway is also involved in glycolysis." (PMID 33968941, 2021). "However, their ability to interfere with the PI3K/Akt/mTOR pathway and their effectiveness in vitro underlined the robust potential of this molecular strategy in cancer therapy." (PMID 33338300, 2021). "Therefore, it is plausible that metformin anti-cancer effects are associated with the inhibition of mTOR activity." (PMID 35008275, 2021). "In addition, we noted that patients in high-risk group were involved in cancer-related pathways such as PI3K/Akt/mTOR pathway and TGF-β/SMAD pathway, which implied a higher risk of progression and metastasis." (PMID 33712026, 2021). "mTOR signaling is hyperactive in a large proportion of human cancers, and accordingly, mutations in distinct components of the pathway have been etiologically involved in several cancers." (PMID 34673573, 2021). "Additionally, p38 inhibition and PI3K/Akt/mTOR activation in cancer cells frequently cause drug resistance." (PMID 34371964, 2021). "Low protein intake had been shown to be more effective in lowering the IGF-1/mTOR nutrient-sensing pathway and is also associated with a reduction in cancer and mortality in the 65 and younger population and protein intake is a key determinant of circulating IGF-1 levels in humans." (PMID 33946428, 2021). "Among them, the mammalian target of rapamycin (mTOR) is responsible of an enzymatic cascade that regulates cell proliferation, autophagy, and apoptosis by participating in multiple signalling pathways, and has also been associated with cancer." (PMID 33923883, 2021). "Also, it implies the need for research of novel treatment strategies, such as the tyrosine kinase inhibitors (TKIs) targeting angiogenic kinases, mTOR-inhibitors in PIK3CA mutated cancers, or immunotherapy with checkpoint inhibitors in PD-L1 positive cancers." (PMID 34394349, 2021). "Mutations that constitutively hyperactivate mTOR contribute to cancer." (PMID 34309456, 2021).
cancer (continued). "One could mention here that the inhibition of mTOR with everolimus causes a hyperactivation of AKT in cancer cells, which could be overcome by a combination with a panAKT inhibitor." (PMID 34064589, 2021). "Mutation has been one of the prime cause of cancer and mutations in upstream and downstream components of mTORC1 may leads to aberrant mTOR signaling and resulting into cancerous conditions." (PMID 34535145, 2021). "The mechanism of fisetin’s anticancer action involves apoptosis, cell cycle arrest, suppression of Akt/mechanistic target of rapamycin (mTOR) signaling pathways, activation of caspase-7 and -9, inhibition of various key enzymes, and downregulation of several genes associated with cancers." (PMID 33920726, 2021). "Abnormal activation of PI3K/mTOR signaling often causes serious diseases, especially cancer." (PMID 34082790, 2021). "A similar reduction in DEPTOR IC50 was observed for the cancer-associated mTOR mutant A1459P." (PMID 34519269, 2021). "In general, the effects of Metformin in cancer are linked to AMPK/mTOR signaling." (PMID 34650055, 2021). "Interestingly, the mTOR pathway has been associated with cancer through its role in the regulation of polyamine dynamics." (PMID 34072010, 2021). "To determine whether STAT3 activation in PTEN-deficient cancer cells can also limit the effects of PI3K/AKT/mTOR inhibitors, we knocked down STAT3 in the HGC-27, MDA-MB436, and 786-O cells, and treated the wild-type and knockdown cells with BEZ235." (PMID 33431808, 2021). "Based on the mechanism of mTOR and previous studies on the mechanism of mTOR in KIRC, we found that the activation of the mTOR pathway in KIRC is still the cause of cancer development; however, our results contradict the conclusion that mutations in the mTOR pathway promote cancer progression." (PMID 34194607, 2021). "LAT1 has been implicated in cancer growth and mTOR signaling." (PMID 34194623, 2021). "Several mutations in the PI3K/AKT/mTOR pathway cause irregular growth of cancer cells." (PMID 33292283, 2020). "mTOR has been identified as a key modulator of autophagy, and dysregulation of this pathway has been implicated in a variety of pathological disorders, including cancer." (PMID 33114161, 2020). "Interestingly, the mechanistic target of rapamycin (mTOR) serine/threonine kinase is a master regulator that participates in two complexes (mTORC1 and mTORC2), and its dysregulation has been implicated in cancer." (PMID 32793477, 2020). "Deregulation of the mTOR pathway is implicated in pathogenesis of several cancer types." (PMID 32899752, 2020). "Moreover, the close association between EGFR and PI3K/AKT/mTOR pathway has been highlighted in some cancer-related studies." (PMID 32231464, 2020). "With regard to mTOR rs2295080, Zhu and colleagues conducted a meta-analysis of seven case–control studies and showed that mTOR rs2295080 may be associated with reduced cancer susceptibility in homozygous, heterozygous and dominant models." (PMID 32597485, 2020). "The ability of the various PLC isoforms to alter the signaling of major oncogenic pathways implicated in cancer like the PI3K/Akt/mTOR, RAS/RAF/MAPK/ERK, and JAK/STAT pathways underscore why it is important that future studies focus on understanding the therapeutic potential of PLCs in cancer." (PMID 32276377, 2020). "Secondly, RNF126 may represent a novel therapeutic target for treating cancer by targeting K48-linked ubiquitination of mTOR." (PMID 32131492, 2020). "The PI3K/AKT/mTOR pathway is another signaling pathway that is often deregulated in human cancer due to mutations/amplifications of upstream growth factor receptors, gene mutations in intrinsic pathway component, or mutations in phosphatases which serve to regulate the pathway (e.g., PTEN)." (PMID 32018226, 2020).